MIR6125 (microRNA 6125)
Synonyms: hsa-mir-6125; mir-6125
Gene: MicroRNA gene on chromosome 12 (62,260,359 to 62,260,454, forward strand). Ensembl gene ENSG00000284360.
Homologues: Orthologues: chimpanzee MIR6125 (100% identical), macaque MIR6125 (100% identical).